STAT3 (signal transducer and activator of transcription 3)
Diseases named in the same sentence as STAT3 in open-access papers (continued):
Sharing a sentence is not in itself a finding about the gene and the disease.
pneumonia (continued). "Furthermore, we revealed that inhibitors targeting Stat3/IL-6 could notably attenuate severe pneumonia during the early infection phase." (PMID 35617354, 2022). "Inhibitors targeting Stat3 or IL-6 could significantly attenuate the pneumonia induced by AC, expanding our understanding of angiostrongyliasis cantonensis and providing effective candidate targets for intervention in AC-induced pneumonia." (PMID 35617354, 2022). "We have recently shown therapeutic efficacy of combined cidofovir (a viral DNA polymerase inhibitor) and etanercept or STAT3 inhibitor treatment in ameliorating lung pathology and protecting mice from lethal OPXV pneumonia." (PMID 36851532, 2023). "Thus, we asked whether intervention with Stat3/IL-6 signaling inhibitors could blunt pneumonia." (PMID 35617354, 2022). "Additionally, targeting the STAT3 signaling pathway with an inhibitor combined with antiviral drug treatment to ameliorate influenza pneumonia is novel and has not been reported previously." (PMID 36851532, 2023). "Moreover, administration of inhibitors targeting Stat3/IL-6 signaling could significantly attenuate the AC-induced pneumonia of non-permissive host mouse, providing an effective candidate target for intervention of this severe parasitic pneumonia." (PMID 35617354, 2022). "Moreover, administration of inhibitors targeting Stat3/IL-6 could attenuate AC-induced pneumonia in nonpermissive host mice, corroborating that Stat3/IL-6 signaling mediates the AC-induced pneumonia and providing an effective candidate target for intervention of parasitic pneumonia." (PMID 35617354, 2022).
laryngeal carcinoma (33 papers, 2011 to 2025). Carcinoma that arises from the laryngeal epithelium. "ERp57 was demonstrated to associate with STAT3 in nucleus and regulate STAT3 activity in radioresistant laryngeal cancer cells." (PMID 38378560, 2024). "For instance, activation of STAT3 is associated with resistance of laryngeal carcinoma cells to ionized radiation; blockade of STAT3 signaling by shRNA sensitized the laryngeal carcinoma cells to radiotherapy both in vitro and in vivo." (PMID 26784960, 2016). "Our data suggest that ERp57 contributes to radioresistance of laryngeal cancer cells by activating the STAT3-Mcl-1 pathway, and this regulation is associated with poor prognosis in laryngeal cancer." (PMID 25605256, 2015). "Our data demonstrated that the increased interaction between ERP57 and STAT3 was associated with the radioresistance of laryngeal cancer cells and enhanced STAT3 activity." (PMID 25605256, 2015). "The present study also provides in vivo evidence that ERp57 expression was tightly associated with the expression of phosphorylated STAT3 or Mcl-1 in laryngeal cancer tissues." (PMID 25605256, 2015). "The results confirmed our hypothesis that treatment of aspernolide A inhibited the activity of STAT3 in laryngeal cancer, suggesting that the apoptosis of laryngeal cancer cells induced by aspernolide A may be caused by the inhibition of STAT3." (PMID 30893785, 2019). "In addition, we showed that ERp57 expression was tightly associated with phosphorylated STAT3 and Mcl-1 expression in laryngeal cancer tissues." (PMID 25605256, 2015). "ERp57 can bind STAT3, a key factor causing resistance in various cancers; therefore, we speculated that the molecular interaction between ERp57 and STAT3 may be linked with the radioresistance of laryngeal cancer." (PMID 25605256, 2015). "Brusatol reversed the Hep-2 cell epithelial-mesenchymal transition (EMT) process, abolishing the Janus kinase 2 (JAK2)/STAT3 signaling pathway in laryngeal cancer cell line." (PMID 38371913, 2023). "For instance, STAT3/HIF-1α signaling pathway activation augments laryngeal cancer cell resistance to cisplatin." (PMID 37628777, 2023). "High cyclin D1 expression was observed in laryngeal carcinomas, and the positive correlation between phosphorylated STAT3 (p‐STAT3) protein and cyclin D1 mRNA suggests that STAT3 promotes cyclin D1 transcription in laryngeal carcinogenesis." (PMID 36419252, 2023). "Recently, the team of Xi Tan has reported that ECD inhibits the growth of laryngeal carcinoma via the STAT3/Cyclin D1 pathway and it was the first study on the mechanism of ECD in the treatment of tumors." (PMID 36313338, 2022). "Esculetin inhibits migration and invasion of laryngeal cancer by inhibiting STAT3 phosphorylation and preventing STAT3 transport into the nucleus." (PMID 33344242, 2020). "At concentrations of 28.87 and 57.74 g/kg, EHD attenuated the protein expression levels of STAT3 and p-STAT3 in laryngeal carcinoma tumour tissue in nude mice." (PMID 32382281, 2020). "STAT3 mediates angiogenesis in laryngeal cancer, and inhibition of the JAK-2/Stat-3 signaling pathway significantly inhibits invasion in vitro and angiogenesis of laryngeal cancer." (PMID 33344242, 2020). "In laryngeal cancer, miR-129-5p can mediate cell proliferation, invasiveness, and migration by suppressing the expression of STAT3." (PMID 31649488, 2019). "Overexpression of SOX18 was found in the tumor tissues of laryngeal carcinoma patients, which regulated cell proliferation, migration, and invasion of laryngeal carcinoma cells through JAK2/STAT3 signaling." (PMID 31189744, 2019). "JAK2/STAT3 signal pathway exists in various types of cancers including laryngeal cancer, which is correlated with cell proliferation, apoptosis, and differentiation." (PMID 31189744, 2019). "The results revealed that SOX18 promoted carcinogenesis in laryngeal carcinoma via activating JAK2/STAT3 signaling." (PMID 31189744, 2019).
laryngeal carcinoma (continued). "It was determined that AG490 inhibits significant proliferation, invasion, vasculogenic mimicry, and induced apoptosis of laryngeal carcinoma cells through downregulation of STAT3, suggesting a potential target for LSCC treatment." (PMID 31781300, 2019). "Our previous study showed that SOCS1 inhibited the laryngeal cancer’s migration and invasion through targeting Stat3." (PMID 31718618, 2019). "Here, we further investigated the role of ERp57 in tumor radioresistance through modulation of STAT3 activity in laryngeal cancer." (PMID 25605256, 2015). "Inhibition of STAT3 activity with a chemical inhibitor or siRNA-mediated depletion of Mcl-1 sensitized radioresistant cells to irradiation, suggesting that the ERp57-STAT3-Mcl-1 axis regulates radioresistance of laryngeal cancer cells." (PMID 25605256, 2015). "We found that both ERp57 and phosphorylated STAT3 were upregulated in laryngeal cancer tissues compared with their normal tissue counterparts, suggesting that ERp57 expression and STAT3 activation are positively correlated in laryngeal cancer." (PMID 25605256, 2015). "We demonstrated that ERp57 modulated radioresistance of laryngeal cancer cells by directly activating STAT3 and, in turn, triggered increased Mcl-1 expression, thereby contributing to tumor radioresistance of laryngeal cancer cells." (PMID 25605256, 2015). "Collectively, our data suggest that the increased interaction between ERp57 and STAT3 in the nucleus is involved with the radioresistance of laryngeal cancer cells." (PMID 25605256, 2015). "Additionally, STAT3 was shown to induce vascular endothelial growth factor (VEGF) secretion in larynx carcinoma cells, which subsequently enhances programmed death ligand 1 (PD-L1) expression in M2-like TAMs." (PMID 40113769, 2025). "Other investigations have suggested that small-molecule inhibitors might be useful in targeting STAT3, for example, cucurbitacin B, which has been used to make laryngeal carcinoma cells more sensitive to cisplatin." (PMID 40729003, 2025). "Downregulation of the phosphorylation levels of STAT3 protein, Akt protein, and NF-kappa B protein resulted in the inhibition of the migratory capacity of laryngeal cancer cells and activation of the mitochondrial apoptotic signaling pathway, thereby inducing apoptosis in laryngeal cancer cells." (PMID 37175435, 2023). "Furthermore, PDIA3 has been shown to promote radioresistance in laryngeal cancer cells by directly activating STAT3 signaling." (PMID 38213579, 2023). "STAT3 expression and phosphorylation increased with malignant progression of laryngeal cancer." (PMID 33344242, 2020). "This suggested that SM‐BFRE might induce the apoptosis of laryngeal cancer cells in vitro and in vivo through the inhibition of STAT3 signalling." (PMID 32869923, 2020). "In addition, Colivelin can reverse the anticancer effect of Esculetin on laryngeal cancer by activating STAT3, further proving that Esculetin functions by inhibiting STAT3 phosphorylation." (PMID 33344242, 2020). "In addition, Western blot analysis demonstrated that SM‐BFRE exerted its anti‐laryngeal cancer effect by activating the mitochondrial apoptotic pathway and inhibiting STAT3 and Akt/NF‐κB signalling pathways." (PMID 32869923, 2020). "The IL-6/STAT3/HIF1 pathway may represent an important target for investigating therapeutic strategies for the treatment of laryngeal cancer." (PMID 28878571, 2017). "While IL-6/STAT3/HIF1 signaling has been reported to play an important role in the treatment of ovarian cell cancer, the issue of whether the IL-6/STAT3/HIF1 pathway may play a role in laryngeal cancer remains uncertain." (PMID 28878571, 2017).
laryngeal carcinoma (continued). "Furthermore, S31-201 treatment reduced the survival of RR-HEp-2 cells in response to various doses of radiation, indicating that STAT3 activity is essential for the radioresistance of laryngeal cancer cells." (PMID 25605256, 2015). "Furthermore, we observed a positive correlation between ERp57 and phosphorylated STAT3 or Mcl-1 and in vivo interactions between ERp57 and STAT3 in human laryngeal cancer." (PMID 25605256, 2015). "To further investigate the physiological relevance of ERp57-STAT3-Mcl-1 regulation in human laryngeal cancer, we first determined the expression of ERp57 and phosphorylated STAT3 using tissue microarrays containing laryngeal cancers and their normal tissue counterparts." (PMID 25605256, 2015). "Thus, our data suggest that increased ERp57-mediated STAT3 regulation confers a poor prognosis in laryngeal cancer." (PMID 25605256, 2015). "Moreover, our findings suggest that high ERp57-mediated STAT3 contributes to poor outcomes in patients with laryngeal cancer in response to radiotherapy, and targeting ERp57-STAT3 is important for enhancing the efficacy of radiotherapy." (PMID 25605256, 2015). "Because ERp57-STAT3 interaction increased STAT3 activity in radioresistant laryngeal cancer cells, we tested whether inhibition of STAT3 activity sensitizes RR-HEp-2 cells." (PMID 25605256, 2015). "This study shows that ERp57 contributes to radioresistance of laryngeal cancer by activating STAT3." (PMID 25605256, 2015). "In accordance, STAT3 reporter assay indicated that ERp57 depletion inhibited STAT3 activity compared to the siRNA controls in the control and irradiated RR-HEp-2 cells, suggesting that ERp57 enhances STAT3 activity in radioresistant laryngeal cancer cells." (PMID 25605256, 2015). "Thus, our data suggest that increased ERp57-STAT3 interaction enhances STAT3 activity in radioresistant laryngeal cancer cells." (PMID 25605256, 2015). "Besides the mitochondrial apoptotic pathway, Western blot analysis indicated that SM‐BFRE might also exert its anti‐laryngeal cancer effect by inhibiting the STAT3 signalling pathway." (PMID 32869923, 2020). "In addition, it was found that SOX18 could also accelerate the phosphorylation of JAK2/STAT3 signaling in laryngeal carcinoma cells." (PMID 31189744, 2019). "Moreover, PDIA3 modulates radioresistance of laryngeal cancer cells by directly activating STAT3 and, in turn, triggers increased Mcl-1 expression, thereby contributing to tumor radioresistance of laryngeal cancer cells and poor outcomes in patients with laryngeal cancer in response to radiotherapy." (PMID 29228584, 2017). "In laryngeal cancer cells, YAP enhances signal transducer and activator of transcription 3 (STAT3) activity, which induces TGF-β signaling to upregulate programmed death-ligand 1 (PD-L1) expression and promote immune evasion." (PMID 40673277, 2025). "Subsequently, we performed Opal Multiplex Immuno‐Histochemistry on tissue sections from laryngeal cancer patients and found a close relationship between CTSL and IL6, JAK and STAT3." (PMID 39893643, 2025). "A recent study indicated that YAP/STAT3 promotes the expression of PD‐L1 in M2‐type macrophages of TAMs by activating VEGFR1‐TGF‐β signaling, thus promoting laryngeal cancer immune evasion." (PMID 37329188, 2023). "Furthermore, our study indicated that SOX18 could stimulate cell proliferation, migration, and invasion of laryngeal carcinoma cells via regulation of JAK2/STAT3 signaling, which could provide a new strategy for laryngeal carcinoma diagnosis and molecular therapies." (PMID 31189744, 2019). "We concluded that aspernolide A induced the apoptosis of laryngeal cancer Hep-2 and TU212 cells by activating the apoptotic signaling pathway in mitochondria and inhibiting the phosphorylation of STAT3, and cyclin was also involved." (PMID 30893785, 2019).
laryngeal carcinoma (continued). "Similarly, in laryngeal carcinoma, YAP/STAT3 was found to promote immune evasion by activating VEGFR1‐TGFβ signaling and enhancing PD‐L1 expression in the M2‐type macrophage of TAMs." (PMID 37329188, 2023). "Weiyi Wang found that dihydroartemisinin could inhibit STAT3 activation, down-regulate MMP-9, and affect the invasion and metastasis of cancer stem cells (CSCs) in laryngeal cancer." (PMID 36941602, 2023). "Consequently, we demonstrated that SOX18 was overexpressed in laryngeal carcinoma cell lines and tissues, and regulated the cell proliferation, cell cycle, apoptosis, migration, and invasion of laryngeal carcinoma cells via JAK2/STAT3 signaling." (PMID 31189744, 2019). "The detection of positive signals in laryngeal cancer tissues (negative control experiments) indicated the in vivo relevance of ERp57-mediated STAT3 regulation." (PMID 25605256, 2015). "Several other studies were performed to determine the influence of the Janus-activated kinase (JAK)/STAT inhibitor AG490 on proliferation and apoptosis of Hep-2 human laryngeal cancer cells and to determine whether there was any inhibition by AG490 of the JAK/STAT3 signaling pathway." (PMID 31781300, 2019). "This study aimed to investigate whether interleukin-6 (IL-6) knockdown may enhance the efficacy of cisplatin in laryngeal cancer stem cells (CSC) and the potential involvement of the signal transducer and activator of transcription 3 (STAT3) and hypoxia-inducible factor 1 (HIF1) in this effect." (PMID 28878571, 2017).
neutropenia (33 papers, 2013 to 2025). A decrease in the number of neutrophils found in the blood. "In fact, a strong correlation has been established between the presence of STAT3 mutations and neutropenia, which is the clinical hallmark of the disease." (PMID 38238319, 2024). "Correlation with clinical characteristics showed that patients with STAT3 mutations were characterized by a higher frequency of neutropenia, anemia, and transfusion-dependent anemia." (PMID 36605429, 2022). "MDS patients with mutated STAT3 were significantly characterized by a higher frequency of BM hypocellularity and neutropenia." (PMID 35267648, 2022). "Another recent study confirmed higher rates of neutropenia, severe neutropenia, and cases requiring treatment in STAT3 mutated samples." (PMID 35646651, 2022). "The study demonstrated that patients with STAT3 mutations are more likely to feature neutropenia and anemias." (PMID 36605429, 2022). "Recently, a significative correlation between STAT3 activating mutations and neutropenia was recently highlighted." (PMID 34685780, 2021). "when we compared groups of patients according to the mutational status of STAT3, we observed a higher frequency of neutropenia, anemia and treatment requirement in those with mutated STAT3." (PMID 34359799, 2021). "New advances were made in the biological characterization of neutropenia in these patients, in particular STAT3 mutations and a discrete immunophenotype are now recognized as relevant features." (PMID 34685780, 2021). "Patients carrying STAT3 mutations more frequently presented with anemia, neutropenia, high LDH, high large granular lymphocyte counts and need for treatment (p = 0.0037)." (PMID 34359799, 2021). "There have been several reports that documented a correlation between the presence of STAT3 mutations and neutropenia, treatment requirement and response to methotrexate in patients with the mutation affecting Y640F." (PMID 34359799, 2021). "Patients with STAT3 mutations had a higher frequency of anemia (p = 0.046), neutropenia (p = 0.005), higher LGL counts (p = 0.039), raised LDH (p = 0.003) and therapy requirement (p = 0.042) compared to patients with wild-type STAT3." (PMID 34359799, 2021). "A significant correlation between the presence of STAT3 mutations and neutropenia/symptomatic disease has already been highlighted in several studies." (PMID 32133291, 2020). "In this regard, recent studies suggest that LGLL patients carrying STAT3 mutations in the DNA binding domain and the coiled-coil domain of this gene also show a high frequency of neutropenia." (PMID 33255665, 2020). "In this different cohort of patients, the presence of STAT3 mutations and neutropenia resulted with an incidence of 85% and 90%, respectively, confirming the findings of the pilot cohort." (PMID 28977911, 2017). "In terms of the mechanisms accounting for neutropenia in CD8+/CD16+/CD56- phenotypic subset characterized by STAT3 mutations, our data suggest a pathogenetic link between STAT3 activation and the development of neutropenia." (PMID 28977911, 2017). "To confirm the correlation among immunophenotype, presence of STAT3 mutations and neutropenia observed in the pilot study group, we evaluated an independent cohort of 20 patients from University Hospital Hematology Unit of Rennes, France." (PMID 28977911, 2017). "This correlation between the presence of STAT3 mutations and neutropenia was demonstrated highly statistically significant (χ2 = 66.5, P < 0.0001)." (PMID 28977911, 2017). "Thirty-four out of 39 neutropenic patients were STAT3 mutated (87.2%), all the patients characterized by severe neutropenia being included among the group of mutated cases." (PMID 28977911, 2017). "Neutropenia has been previously reported in carriers of STAT3 gain-of-function mutations." (PMID 36441748, 2022).